CLDN16 (claudin 16)
Diseases named in the same sentence as CLDN16 in open-access papers (continued):
Sharing a sentence is not in itself a finding about the gene and the disease.
ovarian carcinoma (5 papers, 2008 to 2023). A malignant neoplasm originating from the surface ovarian epithelium. "Among them, CLDN3, CLDN4, CLDN6, CLDN10, CLDN15, and CLDN16 were significantly correlated with overall survival in patients with ovarian cancer." (PMID 34249076, 2021). "Recent studies suggested icb-1 to act as a tumor suppressor in ovarian cancer - its knockdown accelerated growth of various ovarian cancer cell lines and led to upregulation of ovarian cancer markers like CLDN16 and KLK10." (PMID 24826199, 2014). "The vertebrate gene icb-1 previously has been shown to inhibit growth of ovarian cancer cells in vitro and to suppress expression of ovarian cancer biomarkers like kallikrein-related peptidase 10 and claudin 16 or other cancer-related genes activated by estrogens or TNFα." (PMID 24826199, 2014). "Notably, CLDN16 has been characterized as a novel human ovarian cancer-specific transcript using serial analysis of gene expression data." (PMID 18211683, 2008). "Eight genes were overexpressed in ovarian cancer samples compared with normal tissue samples and included CLDN1, CLDN3, CLDN4, CLDN6, CLDN7, CLDN9, CLDN10, and CLDN16." (PMID 34249076, 2021). "In addition to PAX8, COPA complemented with pan-cancer analysis prioritized eight other lineage-restricted outliers (CDH6, CLDN16, FGF18, FOLR1, SLC34A2, SOX17, SPON1, WNT7A) displaying largely confined gene expression in ovarian cancer cell lines and tumor specimens." (PMID 31050342, 2019).
amelogenesis imperfecta (4 papers, 2017 to 2020). Amelogenesis imperfecta (AI) represents a group of developmental conditions affecting the structure and clinical appearance of the enamel of all or nearly all the teeth in a more or less equal manner, and which may be associated with morphologic or biochemical changes elsewhere in the body. "Thus, claudin-3 protein loss-of-function disturbs amelogenesis similar to claudin-16 loss-of-function, where accumulation of enamel matrix protein led to Amelogenesis Imperfecta." (PMID 28596736, 2017). "Mutations in CLDN10, CLDN16, and CLDN19 are associated with amelogenesis imperfecta in humans and in mice, deletion of Cldn3 significantly reduces the enamel volume compared to that of wild-type mice." (PMID 33195274, 2020). "Cldn16 and Cldn19 are also expressed in ameloblast tight junction and loss-of-function mutations of CLDN16 and CLDN19 genes are associated with amelogenesis imperfecta." (PMID 32164158, 2020). "A novel recent finding was that the absence of CLDN16 in ameloblasts explains the clinical finding of amelogenesis imperfecta in FHHNC patients and mice with CLDN16 deficiency." (PMID 29686978, 2018). "Indeed, we demonstrated that loss-of-function mutations in Claudin-16 and -19 (CLDN16 and 19) genes, initially identified to cause Familial Hypomagnesemia with Hypercalciuria and Nephrocalcinosis (FHHNC), also resulted in Amelogenesis Imperfecta (AI)." (PMID 28596736, 2017).
breast carcinoma (4 papers, 2012 to 2024). "Of these 7 DMP-associated genes, hypomethylated CLDN16 is a member of the claudin family modulating cell polarity and is also a biomarker of breast cancer aggressiveness." (PMID 34294135, 2021). "CLDN15 has been shown to be a positive indicator associated with malignant pleural mesothelioma in clinical contexts, while CLDN16 is a predictor of oral squamous cell carcinoma, breast cancer, and thyroid cancer." (PMID 35281827, 2022). "Similar conclusions were found when cells breast cancer cells overexpressing Claudin-16, showed a decrease in invasiveness and motility." (PMID 22559840, 2012). "Claudin-16 (CLDN16) has been shown to be upregulated in breast cancer." (PMID 38540693, 2024).
HELIX syndrome (3 papers, 2020 to 2025). "In the absence of CLDN10b from these segments, e.g., in CLDN10b knockout mice and in TAL from a HELIX syndrome patient, CLDN3 (together with two further claudins, CLDN-16 and -19) is present in all TJ segments, i.e., also in those that are normally occupied by CLDN10b." (PMID 38731882, 2024).
nephrolithiasis (3 papers, 2013 to 2019). The presence of a calculus in the pelvis of the kidney; this is most often composed of mineral salts and proteins. "Besides CLDN16 and CLDN19, in 2009, a genome-wide association study on an Icelandic and Dutch population revealed that a CLDN14 variant (rs219780[C]) is associated with kidney stones too." (PMID 31694170, 2019).
primary hypomagnesemia (3 papers, 2019 to 2025). "Medical management of Renal hypomagnesemia 5 with ocular involvement and its efficacy are typically the same as that for Renal hypomagnesemia 3 caused by variants in CLDN16." (PMID 38606357, 2024).
Bartter syndrome type 4 (2 papers, 2019). A form of Bartter syndrome characterized by maternal polyhydramnios, premature delivery, salt loss, polyuria and sensorineural deafness, associated with hypokalemic and hypochloremic metabolic alkalosis, increased levels of plasma renin and aldosterone, and low to normal blood pressure. "Notably, the CLDN16 gene interaction network appears to be associated with Bartter syndrome type 4, which results from mutations in the BSND gene also affecting the trafficking and function of CIC-K channels." (PMID 31357502, 2019).
amyloidosis (1 paper, 2023). A disorder characterized by the localized or diffuse accumulation of amyloid protein in various anatomic sites. "For example, serpin family B, a protein family that is linked to amyloidosis, and CLDN16, a protein thought to contribute to tau pathology, were found to be positively and negatively correlated with their respective pathology exclusively in female but not male AD patients." (PMID 36899916, 2023).
COVID-19 (1 paper, 2025). A disease caused by infection with severe acute respiratory syndrome coronavirus 2. "Suppression of tight junction genes such as CLDN11, CLDN16, and CLDN18 suggests impaired epithelial barrier integrity, potentially enhancing vascular permeability and pulmonary edema, as reported in COVID-19-related lung injury." (PMID 41200555, 2025).
cutaneous melanoma of the skin (1 paper, 2019). "Our finding suggests that CLDN16 is also associated with cutaneous melanoma of the skin, which seems consistent with the role of CLDN in terms of tumor suppression." (PMID 31146393, 2019).
developmental delay (1 paper, 2020). "Per the literature, TP63 and CLDN16 genes are related to kidney development and developmental delay." (PMID 32211073, 2020).
diabetes (1 paper, 2025). "While it is well established that diabetes increases renal magnesium losses, the specific alterations in claudin-16 regulation remain under investigation." (PMID 40964237, 2025).
Hypercalcemia (1 paper, 2024). An abnormally increased calcium concentration in the blood. "Hypercalcemia and hypermagnesemia were independent from PTH and correlated with higher expression of claudin 16 and 19 in kidneys." (PMID 38386045, 2024).
kidney cancer (1 paper, 2019). Primary or metastatic malignant neoplasm involving the kidney. "We currently perform an in-silico transcriptomic analysis of the CLDN16 interactome in kidney cancer to examine possible associations." (PMID 31357502, 2019).
renal dysplasia (1 paper, 2016). Renal dysplasia is a form of renal malformation in which the kidney(s) are present but their development is abnormal and incomplete. "In Japanese Black cattle, renal dysplasia occurred due to two independent autosomal recessive mutations of the claudin 16 gene (CLDN16), but no phenotypic differences between both types were reported." (PMID 27919260, 2016).
rosacea (1 paper, 2025). A chronic erythematous skin disorder that affects the face. "Compared with healthy controls, KRT6A and KRT16 mRNA levels were significantly upregulated in rosacea, whereas CLDN1, CLDN16, OCLN, and KRT17 showed no significant changes, and CLDN23 was significantly downregulated." (PMID 40346694, 2025).
type 2 diabetic (1 paper, 2024). "Here, we used the type 2 diabetic rat model to induce DN and show a nephroprotective effect following the stimulation of PPAR-α, which stabilized renal tight junction components claudin-2, claudin-5, and claudin-16." (PMID 39684861, 2024).
cancer (5 papers, 2008 to 2019). A tumor composed of atypical neoplastic, often pleomorphic cells that invade other tissues. "CLDN16 has been found to be associated with breast, thyroid, ovarian and lung cancers." (PMID 31146393, 2019).
renal disease (3 papers, 2019 to 2020). "Our report inculcates the idea of studying both the potential translocation of the CLDN16 protein to mitochondria and the functional role of the CLDN16 gene regulatory network in kidney disorders other than FHHNC." (PMID 31357502, 2019). "In this study we aimed to perform an in-depth computational study of the CLDN16 gene and protein so as to gain a better understanding about the latter’s involvement in the pathophysiology of renal disorders." (PMID 31357502, 2019). "Although both renal disorders FHHN and CINF are caused by PCLN-1/CLDN16 mutations, but the clinical features of both diseases are quite different which may be due to specific mutations/deletions in the same gene or through species specificity." (PMID 31952355, 2020). "The CLDN16 interactome was found to consist of 20 genes, mainly involved in kidney diseases." (PMID 31357502, 2019). "According to ToppFun, the CLDN16 interactome is mainly involved in kidney disorders." (PMID 31357502, 2019).
Genetic disorders (2 papers, 2019 to 2025). "Genetic disorders of CLDN16 cause mislocalization of CLDN16, resulting in hypomagnesemia." (PMID 31273276, 2019).
CLDN16 also shares sentences with these, for which no sentence is quoted: tumor (6 papers); Astigmatism (1); atrial septal defect (1); autosomal dominant tubulointerstitial kidney disease (1); Bartter syndrome type 3 (1); chronic kidney disease (1); colon cancer (1); cystinuria (1); Dent disease (1); E. coli infection (1); edema (1); Gitelman syndrome (1); head and neck squamous cell carcinoma (1); hypertrichosis (1); Hypocalcemia (1); ichthyosis-sclerosing cholangitis syndrome (1); invasive breast carcinoma (1); malignant pleural mesothelioma (1); metastasis (1); myopia (1); omphalocele (1); oral squamous cell carcinoma (1); ovarian tumor (1); primary hyperoxaluria type 1 (1); primary hyperparathyroidism (1); Renal hypomagnesemia 3 (1); Strabismus (1); thyroid cancer (1); Umbilical hernia (1).